FMNL3 (formin like 3)
Description:
Plays a role in the regulation of cell morphology and cytoskeletal organization. Required in the control of cell shape and migration. Required for developmental angiogenesis (By similarity). In this process, required for microtubule reorganization and for efficient endothelial cell elongation. In quiescent endothelial cells, triggers rearrangement of the actin cytoskeleton, but does not alter microtubule alignment.
Synonyms: WBP-3; FHOD3; FRL2; WBP3; DKFZp762B245; MGC45819
Tractability: Antibody: UniProt places it where antibodies can reach, with high confidence; its Gene Ontology location is reachable by antibodies, with high confidence; the Human Protein Atlas places it where antibodies can reach. PROTAC: ubiquitination databases record sites on it.
Gene: Protein-coding gene on chromosome 12 (49,636,499 to 49,708,165, reverse strand). Ensembl gene ENSG00000161791.
Subcellular location: Cytoplasm; Cell membrane
Subcellular location (Human Protein Atlas): Golgi apparatus; Plasma membrane; Vesicles; Cytosol
Pathways (Reactome):
Signal Transduction: CDC42 GTPase cycle; RHO GTPases Activate Formins; RHOA GTPase cycle; RHOC GTPase cycle; RHOJ GTPase cycle
Gene Ontology:
Molecular function: protein binding; actin filament binding; GTPase activating protein binding; actin binding; small GTPase binding
Biological process: actin cytoskeleton organization; cell migration; filopodium assembly; cortical actin cytoskeleton organization; regulation of cell shape; cytoskeleton organization; regulation of cell morphogenesis
Cellular component: cytoplasm; cytosol; plasma membrane
Genetic constraint (gnomAD): Loss-of-function variants: 57 observed, 123.58 expected, observed/expected ratio (o/e) 0.46, 90% interval 0.37 to 0.57. The upper end of that interval is the gene's LOEUF score, 0.57, which puts it in group 2 of 6, group 1 being the genes least tolerant of losing a copy. Missense variants: 1,053 observed, 1,362.8 expected, observed/expected ratio (o/e) 0.77, 90% interval 0.73 to 0.81. Synonymous variants: 491 observed, 523.58 expected, observed/expected ratio (o/e) 0.94, 90% interval 0.87 to 1.01.
Homologues: Orthologues: chimpanzee FMNL3 (99% identical), macaque FMNL3 (97% identical), rat Fmnl3 (96% identical), dog FMNL3 (96% identical), pig FMNL3 (96% identical), guinea pig FMNL3 (96% identical), mouse Fmnl3 (92% identical), rabbit FMNL3 (90% identical), tropical clawed frog fmnl3 (79% identical), zebrafish fmnl3 (75% identical), Drosophila melanogaster Frl (46% identical), Caenorhabditis elegans frl-1 (36% identical), and 4 more. Paralogues in human: FMNL2 (71% identical), FMNL1 (58% identical), DAAM1 (24% identical), DAAM2 (24% identical), DIAPH1 (22% identical), DIAPH3 (22% identical), DIAPH2 (21% identical), INF2 (20% identical), FHOD3 (20% identical), FHOD1 (17% identical), FMN2 (16% identical), GRID2IP (16% identical), and 6 more.
Diseases named in the same sentence as FMNL3 in open-access papers:
FMNL3 is named in the same sentence as 24 diseases in open-access papers, as found by Europe PMC text mining. Sharing a sentence is not in itself a finding about the gene and the disease. The quoted sentences say what the papers report.
breast carcinoma (7 papers, 2021 to 2024). "The FMNL3 (Formin-Like 3) gene at 12q13.12 was associated with breast cancer risk with a q-value of 0.013." (PMID 36703164, 2023). "We noticed that FMNL2 and FMNL3 were upregulated in metastatic breast cancer cell lines." (PMID 38296970, 2024). "Some examples of strong correlations are DAAM1 in breast cancer; FMNL1 in nasopharyngeal cancer, non-small cell lung cancer, and clear cell renal cell cancer; and of FMNL3 in colorectal cancer." (PMID 34685534, 2021).
melanoma (5 papers, 2018 to 2023). A malignant, usually aggressive tumor composed of atypical, neoplastic melanocytes. "FMNL3 is related to malignant melanoma and is involved in pathways including GPCR signal transduction and mitotic pre-metaphase." (PMID 35361159, 2022). "Formin 1 (FMN1) is involved in the formation of adherens junctions and actin organization, and other formin family genes (FMNL2/FMNL3) have been shown to play a role in melanoma biology." (PMID 34281234, 2021). "FMNL2 has previously been shown to accumulate at the edge of lamellipodia and at the tips of filopodia in migrating B16-melanoma cells, where in conjunction with FMNL3, it regulates actin filament formation throughout the protruding lamellipodia." (PMID 29930204, 2018). "FMNL3 expression is reported to promote migration and invasion of cancer cells and predicts clinical outcome in different solid cancers such as colorectal carcinoma, squamous cell carcinoma of the tongue, and melanoma." (PMID 36703164, 2023).
ovarian carcinoma (5 papers, 2021 to 2024). A malignant neoplasm originating from the surface ovarian epithelium. "Furthermore, in ovarian cancer, circFOXP1 regulates miR-22 and miR-150-3p through a sponge mechanism, positively influencing the expression of CEBPG and FMNL3, thereby promoting both cancer cell proliferation and enhancing the sensitivity of epithelial ovarian cancer cells to cisplatin." (PMID 39606233, 2024). "Moreover, circFoxp1 could regulate the expression of FMNL3 (formin like 3) and CEBPG (CCAAT enhancer binding protein gamma) in ovarian cancer." (PMID 38152652, 2023).
colorectal cancer (3 papers, 2021 to 2023). A primary or metastatic malignant neoplasm that affects the colon or rectum. "FMNL1 increases the proliferation of leukemia cells, and FMNL3 promotes cell proliferation and clonogenicity in colorectal cancer." (PMID 34193109, 2021).
nasopharyngeal carcinoma (3 papers, 2017 to 2023). A carcinoma arising from the nasopharyngeal epithelium. "In this study, we found elevated FMNL3 protein expression in clinical nasopharyngeal carcinoma (NPC) tissues." (PMID 28198387, 2017).
prostate carcinoma (3 papers, 2016 to 2021). A carcinoma that arises from epithelial cells of the prostate gland. "FMNL3 is required for invasion in PC3 prostate cancer cells and down-regulation of FMNL3 expression is associated with suppression of metastasis." (PMID 27578625, 2016).
tongue squamous cell carcinoma (2 papers, 2020 to 2023). A squamous cell carcinoma that arises from the tongue. "FDD is a component of FMNL3, and high expression of FMNL3 associated with cancer cell migration, invasion, and unfavorable prognosis in tongue squamous cell carcinoma." (PMID 32264916, 2020).
esophageal squamous cell carcinoma (1 paper, 2020). Esophageal squamous cell carcinoma (ESCC) is a type of esophageal carcinoma (EC) that can affect any part of the esophagus, but is usually located in the upper or middle third. "Besides, miR-127 suppressed cell proliferation, migration, and tumorigenicity by targeting formin-like 3 (FMNL3) in human esophageal squamous cell carcinoma." (PMID 32051829, 2020).
Gonococcal infection (1 paper, 2021). "Gonococcal infection did not alter the mRNA abundance of the formins family members with the exception of FMNL3 and DAAM1." (PMID 34962968, 2021).
hepatocellular carcinoma (1 paper, 2022). A malignant tumor that arises from hepatocytes. "A previous study found that LINC01013 directly bound to miR-6795-5p and subsequently relieved FMNL3 in hepatocellular carcinoma cells." (PMID 35449053, 2022).
lymph node metastasis (1 paper, 2017). "FMNL3 expression positively correlated to the clinical stage, T (tumour), N (lymph node metastasis) and M (distant metastasis) classification of NPC patients." (PMID 28198387, 2017).
neuroblastoma (1 paper, 2013). Neuroblastoma (NB) is the most common solid, extracranial childhood tumor. "In particular, FMNL3 has been demonstrated to nucleate filopodia formation and was, therefore, selected to investigate filopodia formation in neuroblastoma cells." (PMID 24223803, 2013). "The FH1-FH2 domain and FH2 domain only FMNL3 clones were kindly gifted by Prof. Henry Higgs (New Hampshire, US) transfected into SK-N-AS neuroblastoma cells and filopodia formation was assessed by immunofluorescent staining of the actin cytoskeleton." (PMID 24223803, 2013). "In this study, we validate the ability of FMNL3 to induce filopodia in neuroblastoma cells and furthermore, implicate FMNL3-induced filopodia formation in the enhanced migratory and invasive potential of cells with reduced miR-335 expression." (PMID 24223803, 2013).
cancer (8 papers, 2017 to 2025). A tumor composed of atypical neoplastic, often pleomorphic cells that invade other tissues. "Additionally, the genes SRGAP2C, LSP1, and FMNL3 have been implicated in the etiology of other types of cancer." (PMID 36703164, 2023). "High FMNL3 expression has previously been linked to poor prognosis in several other cancers." (PMID 36703164, 2023). "Three genes (FMNL3, LPCAT3, and MUC1) were significantly differentially expressed between primary tumors and metastases in TCGA pan-cancer and were associated with overall, disease-specific, and/or progression-free survival." (PMID 40162116, 2025). "Five genes were implicated in the development of other cancer types: SRGAP2C, MAP3K1, FGFR2, LSP1, and FMNL3." (PMID 36703164, 2023). "For example, although these three Rho members similarly interact with Rho effectors thus far identified, RhoA, RhoB, and RhoC act on different effectors, namely ROCKi/2, integrins and formin FMNL3, respectively, and exert different functions in cancer cell migration and morphogenesis." (PMID 29749605, 2018). "Overall, there was an increase in the TR (e.g., WFDC6, GATS, FMNL3, COQ4, and MEOIC) as the cancer stage progressed, whereas a decrease in the TR was noted for PARVA." (PMID 39349823, 2024). "Formin-like 3 (FMNL3) plays a crucial role in cytoskeletal mediation and is potentially a biomarker for cell migration; however, its role in cancer metastasis remains unknown." (PMID 28198387, 2017). "Most notably, meticulous analysis proved that circFoxp1 on exosomes can inhibit miR-22 and miR-150-3p, leading to increased expression of two genes, CCAAT enhancer binding protein gamma (CEBPG) and formin-like 3 (FMNL3), which may affect the resistance of cancer cells to cisplatin." (PMID 36139487, 2022).
tumor (7 papers, 2017 to 2024). "FMNL3 play a critical role in the recruitment of TILs and inflammatory tumor microenvironment." (PMID 38903921, 2024). "Formins, which are potent regulators of actin dynamics, may be involved in tumor invasion and metastasis promotion; and emerging evidence has already implicated FMNL1, FMNL2, and FMNL3 in these processes." (PMID 31861134, 2019). "Interestingly, mesenchyme-like tumour cells showed strong FMNL3 expression while epithelioid tumour cells exhibited slight FMNL3 expression." (PMID 28198387, 2017). "These few reports have supported a possible role of FMNL3 in tumour invasion and metastasis." (PMID 28198387, 2017). "Finally, knockdown of FMNL3 also weakened EMT in tumours in xenographs." (PMID 28198387, 2017). "Consistent with the in vitro experiments results, knockdown of FMNL3 in vivo also led to up-regulation of E-cadherin and down-regulation of Vimentin and MMP-9 in tumour cells in xenographs." (PMID 28198387, 2017).
infection (2 papers, 2016 to 2021). The state of being infected such as from the introduction of a foreign agent such as serum, vaccine, antigenic substance or organism. "To confirm our results, we also examined infection by microscopy after depletion of FHOD1, FMNL3, GRID2IP or INF2; all four decreased bacterial uptake, though depletion of FMNL3 had the weakest effect." (PMID 27152864, 2016). "For instance, the proteins FMNL3, EPB41L1, SSH2, CORO1B and ARPC2 are detected only in E. ruminantium-infected cells, while in FSCN1 and GC, proteins are under-expressed or inhibited by infection." (PMID 34073568, 2021).
FMNL3 also shares sentences with these, for which no sentence is quoted: glioma (2 papers); clear cell renal cell carcinoma (1); dementia (1); esophageal cancer (1); giant cell tumor of bone (1); glioblastoma (1); leukemia (1); non-small cell lung carcinoma (1); oral cancer (1).